RNVU1-24 (RNA, variant U1 small nuclear 24)
Synonyms: RNU1-59P
Gene: Small nuclear RNA gene on chromosome 1 (149,162,783 to 149,162,944, reverse strand). Ensembl gene ENSG00000201699.
Gene Ontology:
Molecular function: pre-mRNA 5'-splice site binding
Biological process: mRNA 5'-splice site recognition
Cellular component: U1 snRNP
Homologues: Orthologues: chimpanzee U1 (81% identical), rabbit U1 (59% identical), zebrafish U1 (42% identical). Paralogues in human: RNVU1-26 (99% identical), RNVU1-25 (97% identical), U1 (96% identical), RNU1-1 (73% identical), RNU1-2 (73% identical), RNU1-27P (73% identical), RNU1-28P (73% identical), RNU1-3 (73% identical), RNU1-4 (73% identical), RNVU1-18 (73% identical), RNVU1-29 (73% identical), RNVU1-31 (73% identical), and 134 more.